TLR2 (toll like receptor 2)
Diseases named in the same sentence as TLR2 in open-access papers (continued):
Sharing a sentence is not in itself a finding about the gene and the disease.
Arthritis (72 papers, 2005 to 2026). Inflammation of a joint. "In the local knee arthritis model, we demonstrated that the destructive arthritis caused by Lpp is TLR2-dependent, possibly due to an excessive inflammatory reaction." (PMID 36262324, 2022). "In a collagen-type II experimental arthritis in mice, periodontitis caused by P. gingivalis and Provotellanigrescens exacerbated arthritis through TLR2-dependent antigen-specific Th17 immune response." (PMID 34209167, 2021). "In a model of zymosan-induced arthritis, it was demonstrated that TLR2-deficient mice showed a decrease in early and late phases of joint inflammation." (PMID 29096690, 2017). "Both C57BL/6- and C3H TLR2-deficient mice infected with B. burgdorferi display significantly worse arthritis and carditis, and we have shown this is mediated primarily by increased recruitment of CD8+ T cells into the infected joint." (PMID 27857714, 2016). "Increased arthritis severity in TLR2−/− mice has been linked to an increase in spirochete burden in joint tissue." (PMID 27857714, 2016). "Among them are investigations on TLR2-deficient mice describing a direct suppression of neutrophils function in these animals and better outcome from arthritis." (PMID 24757287, 2014). "The strong reduction of arthritis was in line with the findings that the local cytokine production was ablated in both TLR2-, and MyD88-deficient mice." (PMID 23148704, 2012). "There is considerable evidence from rodent models that activation of the TLRs can induce or exacerbate inflammatory arthritis, and TLR2 deficient animals exhibited a significantly reduced severity of arthritis." (PMID 20419126, 2010). "In TLR2/C-3 double-deficient mice, synovial infiltrate was significantly decreased in comparison with control (4.0 ± 0.65 in control mice [n = 5] versus 1.9 ± 0.62 in TLR2/C-3 double-deficient mice [n = 5] on day 25 after arthritis onset; P < 0.05)." (PMID 15743485, 2005). "Moreover, consistent with the in vitro data, Tlr2/4-deficient mice exhibited a lesser degree of arthritis severity, including synovial hyperplasia, bone damage, and infiltration of F4/80+ macrophages." (PMID 38426494, 2024). "However, in the hematogenous septic arthritis model, we showed that the destructive arthritis caused by Lpp-expressing S. aureus was TLR2-independent." (PMID 36262324, 2022). "As Lpp receptor, TLR2 plays a role in the host defense against infection, as TLR2 deficient mice infected with the Newman parental strain displayed enhanced arthritis symptoms as well as increased weight loss, mortality and bacterial burden in kidneys compared to the wild-type controls." (PMID 36262324, 2022). "Furthermore, depletion of CD8 cells in TLR2−/− mice has been reported to lower spirochete burden, causing reduced arthritis severity in mice." (PMID 35924250, 2022). "However, in TLR2 deficient mice, Lpp is a strong virulence factor, giving rise to more severe arthritis." (PMID 32404866, 2020). "The data presented here may be of clinical relevance, since activation of TLR2 by P. gingivalis is associated with the aggravation of experimental arthritis in mice." (PMID 30814538, 2019). "However, in a streptococcal cell wall-induced model of arthritis, TLR2-deficient mice show a reduced disease severity, highlighting the variability of results between arthritis models." (PMID 25975607, 2015). "As deficiency in TLR2 or its intracellular signaling molecule MyD88 is sufficient to eliminate B. burgdorferi lipoprotein-induced innate immune cell activation, the observation that arthritis still occurs in TLR2- and MyD88-deficient mice suggests involvement of other inflammatory pathways." (PMID 24967215, 2014). "Similarly, TLR2-deficient mice exhibit lower arthritis scores." (PMID 19134200, 2009). "In recent years, it has been demonstrated that the TLR2/TLR4-NF-κB signaling pathway can be exploited as a target to reduce TLR2/TLR4 protein expression levels to cure gouty arthritis symptoms." (PMID 38652726, 2024).
Arthritis (continued). "Sinomenine has also been effective in improving arthritis in AIA rats by inhibiting the TLR2/NF-κB signaling pathway, a mechanism similarly observed with matrine in alleviating conditions like Staphylococcus-aureus-induced endometritis." (PMID 38276618, 2024). "Surprisingly, the WT/young group had the highest frequency of clinical arthritis (47%) among the groups on day 10 after infection, while the TLR2−/−/old group had the lowest frequency (23%)." (PMID 36808423, 2023). "Meanwhile, evidence from animal models suggested that EA can also alleviate arthritis by inhibiting TLR2 and/or TLR4 signaling." (PMID 36785752, 2023). "By co-immunostaining we found that the co-localization of TLR2 with RANK was significantly greater in CIA mice relative to vehicle-treated mice, suggesting expression of TLR2 was increased in RANK+ monocytes during arthritis progression." (PMID 37204303, 2023). "The anti-arthritic effect of TQ (10 mg/kg in 0.1% DMSO) was observed in a rat model of arthritis with a marked reduction in the mRNA levels of toll-like receptor 2 (TLR2), TLR4, IL-1, NF-κB, and TNF-α." (PMID 34073784, 2021). "A previously published study stated that the relative abundance of gut Candidatus_Saccharimonas was negatively correlated with the expression levels of cadherin-11, IL-17α, and TLR2 in the adjuvant-induced arthritis rat model." (PMID 34956162, 2021). "With regards to the effect of Lpp, we observed that the Newman parental strain induced significantly more severe clinical arthritis than the Δlgt mutant strain in the TLR2−/− mice on days 7 (P = 0.002) and 10 (P = 0.002) post-infection." (PMID 32404866, 2020). "Here, we show that a single intra-articular injection of S. aureus lipoproteins (Lpps) into mouse knee joints induced chronic destructive macroscopic arthritis through TLR2." (PMID 31226163, 2019). "In murine arthritis models, deficiencies in TLR4 and TLR2 inflicted divergent results, with TLR2 showing disease-mitigating effects, while TLR4 stimulation triggered arthritis." (PMID 31266174, 2019). "LPS (ligand for toll-like receptors, TLR4/TLR2) or lipomannan (ligand for TLR2) enhances the incidence and severity of the antibody initiated disease by decreasing the threshold for arthritis induction." (PMID 29495570, 2018). "The plasmid backbone and multiple immunoregulatory properties of IL-18 appear to play a major role in the pIL-18 coadministration with rIL-4-mediated immunomodulation of arthritis through blocking the TLR2/MyD88/NF-kappa B signaling pathway." (PMID 29854762, 2018). "This was surprising as P. gingivalis was reported to trigger the TLR2 pathway which in turn was described to promote spontaneous arthritis in SKG mice." (PMID 30310087, 2018). "The plasmid backbone and multiple immunoregulatory properties of IL-18 appeared to play the major role in the pIL-18 coadministration with rIL-4-mediated immunomodulation of arthritis through blocking the TLR2/MyD88/NF-kappa B signaling pathway." (PMID 29854762, 2018). "Studies reported that ligands for TLRs (including TLR-2, 3, 4, 9) induced or exacerbated arthritis in experimental models." (PMID 28418842, 2017). "To investigate this phenomenon further, we infected C3H WT and C3H TLR2−/− mice with B. burgdorferi in both rear footpads and followed the development of arthritis." (PMID 27857714, 2016). "As previously reported, arthritis severity scores in TLR2−/− mice were significantly increased over WT control mice at day 21 postinfection." (PMID 27857714, 2016). "We presume that TLR2 and TLR9 can also be activated by viral components (like EBV) in the synovial compartment, a mechanism causing exacerbation of arthritis in susceptible RA patients." (PMID 26759164, 2016). "It was suggested that the enhanced arthritis of TLR2−/− mice was due to unregulated local chemokine production by synoviocytes." (PMID 27857714, 2016).
Arthritis (continued). "Intradermal inoculation of B. burgdorferi into C3H TLR2−/− mice results in exacerbated arthritis compared with WT C3H and has been correlated with increased numbers of T cells within the joint tissue." (PMID 27857714, 2016). "Sections of both ankle joint and heart tissue from control-treated and T cell-depleted TLR2−/− mice were processed for histology by H&E staining and scored for arthritis and carditis severity." (PMID 27857714, 2016). "Zymosan-induced arthritis was found to be dependent on TLR2 activation as disease was substantially attenuated in Tlr2−/− mice." (PMID 27199979, 2016). "Increased expression of TLR2 has been demonstrated in collagen-induced arthritis, and streptococcal cell wall (SCW)-induced arthritis does not develop in TLR2-deficient mice." (PMID 26055925, 2015). "Arthritis was induced by intra-articular injection of zymosan, a ligand for Toll-like receptor 2 (TLR2)." (PMID 24757287, 2014). "Low-dose activation of TLR7 with a small synthetic ligand has been shown to induce tolerance of TLR2, 7, and 9 signaling and to suppress disease in a serum transfer model of arthritis." (PMID 22691272, 2012). "In animal models intra-articular injection of the TLR2 leads to development of destructive arthritis in mice and TLR2/MyD88 knockout mice are protected from SWC induced joint inflammation." (PMID 21858161, 2011). "In that study, TLR2−/− mice had reduced FoxP3 expression, greater IL-17 expression, and increase arthritis severity, while TLR4−/− mice had a lesser severity of arthritis, and lowered IL-17 expression." (PMID 21695198, 2011). "TLR2 and 4 were reported to be involved in the chronicity and erosive destruction of streptococcal cell wall induced arthritis and spontaneous arthritis in IL-1 receptor antagonist-knockout mice." (PMID 20500834, 2010). "Studies in animal models have established that the TLR2 status influences the outcome of adjuvant-induced arthritis and streptococcal cell wall arthritis." (PMID 19134200, 2009). "RA SFs, activated via TLR2, were suggested to contribute to arthritis development by secretion of chemokines." (PMID 19442276, 2009). "We have investigated the mechanisms of inflammation in murine zymosan-induced arthritis (ZIA) in the light of recent data on the roles of Toll-like receptor 2 (TLR2) and Dectin-1 in the activation of monocyte/macrophages by zymosan." (PMID 15743485, 2005). "Abundant lipoproteins on Lyme spirochete surface activate TLR2 signaling, which induces inflammatory responses to control spirochetes in the joints and mitigate B. burgdorferi infection, but these inflammatory factors can also enhance arthritis severity." (PMID 35924250, 2022). "Furthermore, depletion of CD8 cells in TLR2−/− mice lowered spirochete burden and reduced arthritis severity in mice." (PMID 35924250, 2022). "Importantly, TLR2 and TLR4 are crucial for autoantibody generation in lupus and a TLR4-deficient arthritis model shows attenuated disease and lower titers of autoantibodies." (PMID 34381449, 2021). "Tolerance to HSP65 and arthritis prevention induced by the recombinant L. lactis was associated with increase in IL-10 production by B cells and it was dependent on LAP+ T cells, IL-10 and TLR2 signaling." (PMID 33072101, 2020). "This hypothesis was also enlightened further with upregulation of COL9A2, which shows increase in its expression in arthritis and TLR2, which will upregulate MMP increasing collagenolysis and aggrecanolysis." (PMID 29731966, 2018). "However, the mono-colonization of these mice with Lactobacillus induced arthritis via activation of Toll-like receptor 2 (TLR2) and TLR4." (PMID 28598360, 2017). "Due to the low numbers of animals in this experiment, this result was not statistically significant, but along with our previous data, suggests that CD8+ T cells are the cells responsible for the increased inflammation and arthritis severity seen in TLR2−/− mice infected with B. burgdorferi." (PMID 27857714, 2016).
Arthritis (continued). "Furthermore, mono-colonisation with Lactobacillus bifidus was shown to be sufficient for inducing joint inflammation in a mouse model of spontaneous arthritis via TLR2- and TLR4-dependent signalling affecting the balance between Treg, Th17 and Th1 in the gut." (PMID 26822477, 2016). "It is tempting to speculate that the reduced numbers of NKT cells in the infected joints of TLR2−/− mice might be responsible for the increased arthritis severity and spirochete loads in this tissue." (PMID 27857714, 2016). "In addition, an anti-TLR2 antibody has recently been demonstrated to decrease inflammation in a mouse model of arthritis, and blockade of TLR2 to reduce spontaneous cytokine release from synovial explant cultures in RA." (PMID 27716430, 2016). "Production of type I IFN has been linked to arthritis development in B. burgdorferi-infected mice, and its production has been shown to be independent of TLR2 signaling." (PMID 27857714, 2016). "Moreover, zymosan, a polysaccharide from the cell wall of Saccharomyces cerevisiae that binds TLR2, has been used to induce experimental arthritis in mice." (PMID 27199979, 2016). "We conclude that TLR2 regulates the destructive potential of neutrophils and its targeting might limit joint alterations in arthritis." (PMID 24757287, 2014). "TLR2-driven arthritis was induced by i.a. injection of zymosan into BALB/c mice." (PMID 24757287, 2014). "Various studies have shown the role of TLR2 signaling for the development of arthritis." (PMID 24757287, 2014). "In mice, the expression of TLR2 resulted in experimentally induced arthritis." (PMID 24134665, 2013). "However, in this experimental model, arthritis develops via zymosan-mediated activation of classic and alternative complement pathways and the engagement of Toll-like receptor 2 (TLR2) on monocytes and neutrophils." (PMID 22830570, 2012). "Furthermore, several animal models use bacterial wall components and peptidoglycans (PG), known to activate TLR2, to induce experimental arthritis." (PMID 21345222, 2011). "Increased expression of TLR2 has been demonstrated in collagen induced arthritis, and TLR2 deficient mice do not develop streptococcal cell wall (SCW) induced arthritis." (PMID 21858161, 2011). "In the early phase of arthritis TLR2 plays a vital role, and in the later phase the development of a secondary immune response to zymosan may contribute to joint inflammation." (PMID 15743485, 2005). "The data in human arthritis would also support such a role for TLR2." (PMID 15743485, 2005). "In TLR2-/- mice, synovial infiltrate was significantly decreased in comparison with TLR2+/+ mice (4.9 ± 0.33 in TLR2+/+ mice [n = 15] versus 3.1 ± 0.67 in TLR2-/- mice [n = 12] on day 25 after arthritis onset; P < 0.045)." (PMID 15743485, 2005). "Importantly, the combination of Lpp expression (Newman parental strain) and lack of TLR2 lead to the most severe disease outcome, underlining the importance of TLR2 for protection in the hematogenous arthritis model." (PMID 32404866, 2020). "However, how depletion of CD4+ or CD8+ cells, both of which are expressed on some NKT cell subsets, could reduce B. burgdorferi tissue loads and increase arthritis severity in the TLR2−/− mice is unclear." (PMID 27857714, 2016). "Therefore, we conclude that targeting TLR2 signaling on neutrophils may limit bone resorption and joint damage in arthritis." (PMID 24757287, 2014). "Knockout models using B6 TLR2−/− or MyD88−/− mice have shown the important role of NF-κB in host defense, but because these mice have such a severe innate defect in bacterial defense, elucidating the role of NF-κB in arthritis using these models has remained difficult." (PMID 24967703, 2014).
Arthritis (continued). "Results obtained in a mouse model of spontaneous arthritis showing that TLR2 stimulation has been significant for the functioning of Tregs and the regulation of IFNγ–producing Th1 cells imply that the beneficial impact on IBDs might rely, at least partially, on the rBanLec-TLR2 interaction." (PMID 40305159, 2025). "Some findings indicated more severe arthritis in TLR2−/− mice than wild-type (WT) controls and that TLR2−/− mice promote the effector phase of arthritis through decreased IL-10 production by macrophages." (PMID 35241180, 2022). "Considering differential roles of TLR2 and TLR4 in IL1rn−/− arthritis, we sequenced samples of IL1rn−/−Tlr2−/− and IL1rn−/−Tlr4−/− mice in parallel." (PMID 28645307, 2017). "Given that additional TLR2 deficiency did not affect the microbiota of IL1rn−/− mice to a major extent, we speculate that severe arthritis in IL1rn−/−Tlr2−/− mice is due to the altered host immune response, specifically reduced function of Treg cells, rather than alteration in the microbiome." (PMID 28645307, 2017). "Intra-articular injection of the TLR2 and NOD2 ligand PG led to development of destructive arthritis in mice." (PMID 21345222, 2011). "In particular, injection of TLR2 and TLR9 ligands, peptidoglycan (PGN) and CpG DNA, into articular cavities induces arthritis in mice." (PMID 20500834, 2010). "The intra-articular triggering of TLRs led to the joint inflammation, and TLR2 and TLR4 have been shown to play a critical role in bacterial cell wall-induced arthritis." (PMID 18847495, 2008). "Mice lacking TLR2 showed reduced frequency and less severe arthritis compared to controls in an antibiotic-killed S. aureus-induced arthritis model." (PMID 41170422, 2025). "Of note, most of the mice that succumbed to the disease in the TLR2−/−/Newman group exhibited severe clinical arthritis, which were radiologically not possible to examine due to the deaths of animals prior to the study endpoint." (PMID 32404866, 2020). "We confirmed a similar relevance for TLR2 for the effect of Hsp65-Lac in the prevention of the acute model of arthritis, since TLR2–/– mice were not affected by Hsp65-lac treatment." (PMID 33072101, 2020). "The TLR2-/- mice barely developed clinical signs of arthritis, and no joint destruction was observed compared to that of the wild-type mice, of which 100% presented joint erosions." (PMID 31226163, 2019). "In addition, the knockout of TLR9 resulted in no progression of arthritis, suggesting that these three TLRs (i.e., TLR2, TLR4, and TLR9) have different relationships with the induction of arthritis and IL-17 production." (PMID 30103522, 2018). "In contrast, TLR2−/− mice have exacerbated levels of neutrophils and macrophages in the infected joints, and these levels are decreased with T cell depletion, but only CD8+ T cell depletion appears to lower arthritis severity." (PMID 27857714, 2016). "In a mouse model of arthritis, mice lacking TLR2 showed enhanced histopathological scores of arthritis by a shift in T cell balance from Th2 and T regulatory cells toward pathogenic Th1 cells." (PMID 25132835, 2014). "While the TLR/MyD88 signaling pathway is the main pathway contributing to B. burgdorferi lipoprotein mediated inflammation in vitro, arthritis and carditis still develop in vivo in the absence of TLR2 or MyD88 expression." (PMID 24967215, 2014). "Finally, TLR2−/− and TLR4−/− mice were found to have opposite phenotypes in a spontaneous model of murine arthritis." (PMID 21695198, 2011). "Furthermore, TLR2 intensities correlated with the levels of several inflammatory cytokines and disease activity markers and systemic scores and were higher in patients with arthritis than in those without arthritis." (PMID 35715478, 2022). "The inhibitory effects of TLR2 and TLR9 in STA pathogenesis can not explain the EFL2’s anti-inflammatory role in arthritis." (PMID 34950033, 2021).
Arthritis (continued). "In contrast to PIA, the acute phase of SCW‐induced arthritis is TLR2 dependent but shifts towards a TLR4 dependency in the chronic phase, in which TLR2 is no longer relevant." (PMID 29992753, 2018). "Furthermore, numbers of circulating TLR2-positive cells were increased in patients with AOSD and arthritis compared to that in patients without arthritis." (PMID 35715478, 2022).